BMAL1 (basic helix-loop-helix ARNT like 1)
Diseases named in the same sentence as BMAL1 in open-access papers (continued):
Sharing a sentence is not in itself a finding about the gene and the disease.
metabolic syndrome (29 papers, 2008 to 2025). A cluster of metabolic risk factors for CARDIOVASCULAR DISEASES and TYPE 2 DIABETES MELLITUS. "In particular, the polymorphisms in CLOCK and BMAL1 genes were reported to be significantly related to cardiovascular disease, metabolic syndrome, sleep reduction, and evening preference." (PMID 38612648, 2024). "The Bmal1 SNP rs11022775 (OR 0.70, 95% CI 0.52–0.94; P = 0.016) was negatively associated with dyslipidemia." (PMID 34141862, 2021). "The methylation status of CpG sites located in clock genes (Clock, Bmal1, and Per2) is associated with obesity, metabolic syndrome and weight loss." (PMID 31139087, 2019). "In conclusion, the results in this study revealed that loss of the functions of BMAL1 leads to the development of ectopic fat formation and dyslipidemia." (PMID 21966465, 2011). "However, several polymorphisms associated with metabolic syndrome were identified in the SHR Bmal1 promoter, suggesting a potential link between the circadian system and the SHR pathological phenotype." (PMID 24086613, 2013). "Several polymorphisms associated with metabolic syndrome were identified in the SHR Bmal1 promoter." (PMID 24086613, 2013). "Consequently, we were led to conclude that the loss of the Bmal1 gene induced metabolic syndrome." (PMID 21966465, 2011). "Therefore, in this study, we aimed to study whether loss of BMAL1 functions induces metabolic syndrome." (PMID 21966465, 2011). "Therefore, in this study, we examined whether loss of BMAL1 function is capable of inducing metabolic syndrome." (PMID 21966465, 2011). "Clock genes are linked directly to metabolic syndromes; polymorphisms circadian clock genes CLOCK, BMAL1, Per1/2 and Cry1/2 have been associated with metabolic disorders, including neuropsychiatric or neurodegenerative diseases." (PMID 33184471, 2020). "Liver-specific Bmal1-/- knock-out mice exhibit hypoglycemia during fasting, and greater glucose clearance despite normal insulin production and dyslipidemia, including high circulating FFA levels and high hepatic TGs." (PMID 31139087, 2019). "Bmal1 mutant mice also have disrupted circadian rhythmicity, disrupted adipogenesis, and demonstrate markers of metabolic syndrome (e.g., higher levels of triglycerides and glucose)." (PMID 24313168, 2013). "Although both Bmal1 -/- mice and Clock mutant mice develop metabolic syndrome-like symptoms, Bmal1 -/- mice are thin and Clock mutant mice are obese (28, 29, this study)." (PMID 21966465, 2011). "Our findings on the metabolic profile and associated hepatic lipid metabolism in the absence of Bmal1 in hepatocytes provides new insights into metabolic syndromes from the perspective of liver CR disturbances." (PMID 38892255, 2024). "In individuals with metabolic syndrome, dysregulated BMAL1 function in adipose tissue leads to imbalances in metabolic processes (such as alterations in NADPH levels, mitochondrial electron transport, diurnal activation of UCP1, and inhibition of NF-κB, ultimately disrupting normal energy balance)." (PMID 39728504, 2024). "Collectively, these findings highlight the integral role of circadian rhythms, particularly through Bmal1, in maintaining metabolic homeostasis, and further demonstrate the potential consequences of Bmal1 dysfunction, including metabolic syndrome and related disorders." (PMID 39728504, 2024). "CLOCK and BMAL1 play a role in protecting the body against symptoms of metabolic syndrome." (PMID 32344535, 2020). "Changes in Per2, Bmal1 and Cry1 mRNA expression are related to human metabolic syndrome." (PMID 25799429, 2015). "Therefore, we were led to conclude that BMAL1 is a crucial factor in the regulation of energy homeostasis, and disorders of the functions of BMAL1 lead to the development of metabolic syndrome." (PMID 21966465, 2011). "In metabolic syndrome patients, the function of BMAL1 is dysregulated in visceral adipose tissue." (PMID 21966465, 2011).
metabolic syndrome (continued). "BMAL1 activity is disturbed in the visceral adipose tissue of metabolic syndrome patients." (PMID 21966465, 2011). "Other studies have shown associations between CRY1 and CRY2 polymorphisms and blood pressure in patients with metabolic syndrome, or associations between PER2 and BMAL1 polymorphisms and the non-dipper phenotype in 372 young hypertensive patients." (PMID 37298261, 2023). "We show here that global (whole body) Bmal1 -/- mice, derived from the embryonic stem (ES) cells of C57BL/6J mice, exhibited a metabolic syndrome-like onset, i.e., elevation of the level of circulating fatty acids, including TG, free fatty acids, and low-density lipoprotein (LDL)-cholesterol." (PMID 21966465, 2011). "In contrast, although NOB potently protects against metabolic syndrome in DIO mice and db/db mice in a clock-dependent manner, it directly binds to and activates RORs, which are components within the forward limb of the circadian clock system, and enhances Bmal1 transcription." (PMID 37299510, 2023). "Therefore, although we do not exclude the possibility that, in Bmal1 -/- mice, impaired insulin secretion is partly responsible for development of dyslipidemia, its contribution via acceleration of lipolysis is relatively smaller." (PMID 21966465, 2011). "Disruption of this rhythm in the absence of BMAL1 leads to elevated phosphatidylcholine levels, resulting in altered lipoprotein profiles, an increase in non-HDL cholesterol, and the development of conditions such as fatty liver, dyslipidemia, and metabolic syndrome." (PMID 40243466, 2025).
melanoma (28 papers, 2017 to 2025). A malignant, usually aggressive tumor composed of atypical, neoplastic melanocytes. "On the one hand, loss of Bmal1 in murine melanoma models disrupted circadian rhythmicity, suppressed hypoxia‐related gene expression, and inhibited tumor growth." (PMID 41085102, 2025). "Here the authors show that ectopic expression of Bmal1 promotes an immune resistant mesenchymal melanoma cell state associated with increased AP-1 activity." (PMID 38245503, 2024). "In melanoma, higher BMAL1 is associated with higher T-lymphocyte infiltration, higher PD-1 and PD-L1 expression, better objective response to anti-PD1 immunotherapy and improved overall patient survival." (PMID 33794967, 2021). "In fact, we showed that high BMAL1 expression in pretreatment melanoma samples is associated with clinical benefit from anti-PD1 immunotherapy." (PMID 29946530, 2018). "High BMAL1 expression was also associated with impaired DNA-repair capacity in human melanoma cell lines from the Cancer Cell Line Encyclopedia." (PMID 29946530, 2018). "Notably, Hif1α or Sox9 expression in melanoma is associated with tumorigenesis, suggesting their putative roles in Bmal1-dependent B16-F10 tumorigenesis." (PMID 38245503, 2024). "Loss of Bmal1 in YUMM2.1 or B16-F10 melanoma cells eliminates clock function and diminishes hypoxic gene expression and tumorigenesis, which could be rescued by ectopic expression of HIF1α in YUMM2.1 cells." (PMID 38245503, 2024). "Thus, our mouse melanoma model reveals an immune resistant, ectopic Bmal1-driven AP-1-associated Sox9high mesenchymal state that is found in immunotherapy resistant human melanomas." (PMID 38245503, 2024). "In melanoma, BMAL1 overexpression is associated with TLR cascade and signaling pathways." (PMID 33794967, 2021). "On the other hand, overexpression of Bmal1 enhanced melanoma cell plasticity by promoting a transition from a Sox10high proliferative state to a Sox9high mesenchymal‐like, immune‐tolerant state." (PMID 41085102, 2025). "Bmal1 was shown to exert cell state‐dependent effects on melanoma immunity, tumorigenicity, and metastasis." (PMID 41085102, 2025). "Collectively, the evidence supports an interaction between Bmal1 proteins and Myh9 in mouse and human melanoma cell lines." (PMID 38245503, 2024). "As a key circadian regulator in melanoma, downregulation of BMAL1 facilitates melanoma growth and metastasis, and compromises patient survival." (PMID 39213172, 2024). "To investigate the association between metabolic activity and circadian rhythms in these contexts, we generated Bmal1::luciferase reporter lines from a library of human patient-derived melanoma lines and compared their circadian and metabolic activity." (PMID 39008664, 2024). "As such, we explore here the effects of the circadian regulator Bmal1 on mouse melanoma cell state, tumorigenesis and therapeutic resistance." (PMID 38245503, 2024). "BMAL1 also transcriptionally regulates MiTF in human melanoma cells to influence melanin synthesis against UVB irradiation." (PMID 38245503, 2024). "In line with our results, Gaddameedhi’s lab recently reported that MITF shows a rhythmic expression via BMAL1 interaction with the MITF promoter in human melanoma cells." (PMID 35562405, 2022). "There is evidence that compared to BMAL1 expression in patients with healthy skin, BMAL1 expression in melanoma patients is significantly changed, which represents a dysfunctional circadian clock and correlates positively with T-cell infiltration/activation." (PMID 35326729, 2022). "Metastatic melanoma patients with high BMAL1 expressing tumors demonstrate improved survival response to anti-PD-1 immunotherapy compared to low BMAL1 expressing patients (50% overall survival at ~ 105 months vs ~ 70 months, respectively; 66)." (PMID 33794967, 2021). "Higher BMAL1 expression is correlated with higher CTLA-4 expression in melanoma tumors and their infiltrating T lymphocytes." (PMID 33794967, 2021).
melanoma (continued). "Next, we injected the control (B16-CTL) and Bmal1 KO melanoma cells (B16-Bmal1-KO) into mice subcutaneously and subjected them to drug treatment after detectable tumor formation." (PMID 33579708, 2021). "Within the tumor microenvironment, macrophage Bmal1 gene deletion leads to compromised anti-tumor immunity and accelerated tumor growth in a mouse melanoma model." (PMID 32396064, 2020). "Subsequently, we employed a mouse model of melanoma through subcutaneous injection of B16-F10 melanoma cells to assess the impact of myeloid Bmal1 deletion on tumor growth." (PMID 32396064, 2020). "Melanoma patients with high expression levels of BMAL1 have increased T-cell activity, a better response to anti-PD1 immunotherapy and increased overall survival, as compared to patients with low BMAL1 levels." (PMID 33089179, 2019). "The high incidence of antigenic peptides observed in metastatic melanomas with high BMAL1 expression was accompanied by increased expression of cytotoxic T-cell activity markers in the tumor bulk and better prognosis." (PMID 29946530, 2018). "Here, we show that Bmal1 has a context-dependent role in mouse melanoma tumor growth." (PMID 38245503, 2024). "Our work describes a link between Bmal1, Myh9, mouse melanoma cell plasticity, and tumor immunity." (PMID 38245503, 2024). "Control melanoma cells (B16-CTL) exhibited marked circadian oscillation of the clock reporter activity upon dex synchronization, but rhythms were completely abrogated in Bmal1-deficient cells (B16-Bmal1-KO)." (PMID 33579708, 2021). "Evidence indicates that compared with the expression of BMAL1 in patients with healthy skin, the expression of BMAL1 in patients with melanoma is remarkably disrupted, which represents a dysfunctional circadian clock, and has been positively correlated with the infiltration/activation of T cells." (PMID 33752691, 2021). "By using the B16-F10 melanoma model, we obtained results that demonstrate that the regulatory axis between Bmal1 and Hif-1α dictates macrophage energy investment that is relevant for discrete activation or polarization states, including activation of M1 and tumor-associated macrophages." (PMID 32396064, 2020). "Additionally, chromatin-immunoprecipitation (ChIP) showed that the circadian clock protein BMAL1 transcriptionally binds to the promoter region of the human XPA gene in human melanoma cells, further supporting a direct link with the endogenous circadian clock." (PMID 29581861, 2018). "Therefore, the present data indicate that BMAL1 expression in melanoma patients must be considered as a relevant marker for immunotherapy efficacy." (PMID 29946530, 2018). "Studies have demonstrated that CLOCK and BMAL1 affect cell proliferation by regulating the expression of Wee1, a kinase that inhibits cell cycle progression from G2 to M phase, suggesting a mechanism where disruptions in circadian rhythms could promote uncontrolled cell growth typical of melanoma." (PMID 40191195, 2025). "Collectively, our findings indicate that knockdown of Myh9 phenocopies ectopic expression of Bmal1 proteins in YUMM2.1 cells and confers an immune resistant mesenchymal melanoma cell state." (PMID 38245503, 2024). "When it comes to melanoma, higher CTL infiltration along with higher PD-1/L1 expression was found to be correlated with higher BMAL1 during anti-PD-1 immunotherapy clinical settings." (PMID 37183243, 2023). "Studies have shown that the circadian clock gene BMAL1 affects dendritic cells (DCs) and CD8 T cells through the co-stimulatory molecule CD80, thereby exerting circadian anti-tumor functions that control melanoma volume." (PMID 37323834, 2023). "By probing tyrosinase expression in the tumor bulk, melanoma cells (TYROSINASE-positive cells) were selected, which demonstrated higher levels of BMAL1 expression and increased frequency of BMAL1-positive cells." (PMID 35562405, 2022).
melanoma (continued). "Among the Bmal1 interactors, we chose to focus on Myh9 (non-muscle myosin IIA) in depth, because it has been implicated in melanoma tumorigenesis and drug resistance, and thought to be a tumor suppressor in several tumor models." (PMID 38245503, 2024). "Altogether, however, biological insights from the sequencing and proteomic data are corroborated by functional luciferase reporter assays and tumorigenesis studies, supporting the connections between Bmal1, Myh9, MRTF/SRF, AP-1, melanoma cell states and immune evasion." (PMID 38245503, 2024). "To determine whether time-modulated drug activity on the mouse melanoma was core clock dependent, we generated CRISPR-control (B16-CTL) and Bmal1 knockout (B16-Bmal1-KO) melanoma cells stably expressing Per2 promoter–driven luciferase (pPer2-dLuc)." (PMID 33579708, 2021). "In contrast to the control tumor, the Bmal1 knockout melanoma (B16-Bmal1-KO) was not significantly suppressed by the HSP90 inhibitor at ZT15." (PMID 33579708, 2021). "Importantly, the expression of BMAL1 was a prognostic factor independent of the percentage of leukocyte, monocyte, and neutrophil infiltration in TCGA melanomas." (PMID 29946530, 2018). "Recently, we have demonstrated that a non-metastatic model of melanoma leads to a systemic chronodisruption in tumor-adjacent skin, lungs, liver, and SCN, as in these tissues the rhythmic expression of Bmal1 was lost in tumor-bearing mice." (PMID 29946530, 2018).
osteosarcoma (27 papers, 2008 to 2025). A usually aggressive malignant bone-forming mesenchymal neoplasm, predominantly affecting adolescents and young adults. "To experimentally verify our prediction, we have constitutively overexpressed Rora in human osteosarcoma cells harbouring a circadian reporter (Bmal1-promoter-luc) which resulted in loss of oscillations, in agreement with our modelling data." (PMID 22194677, 2011). "While p21 has a minimal role, BMAL1 suppression attenuates MLN4924’s antiproliferative effect, indicating that MLN4924-induced growth inhibition in osteosarcoma cells is mediated primarily by BMAL1." (PMID 40046513, 2025). "ChIP-seq experiments of both factors in the same osteosarcoma cell line showed that BMAL1 and HIF1α share a large portion of binding sites on chromatin, which constitutes approximately a third of all HIF1α targets and a quarter of BMAL1 targets." (PMID 37601651, 2023). "The toxicity of selected molecules was assessed by MTT assay using human osteosarcoma (U2OS Bmal1-dLuc where the destabilized form of Luciferase (Luc) gene fused with Bmal1 promoter) cells at concentrations of 20, 10, and 2.5 μM." (PMID 36347873, 2022). "Human osteosarcoma U2OS cells were engineered to express firefly luciferase reporters under control of BMAL1 promoter (U2OS-C26) and PER2 promoter (U2OS-D15), respectively." (PMID 34905700, 2021). "Transfection of Bmal1-dLuc U2OS osteosarcoma cells containing a luciferase reporter driven by the Bmal1 promoter with miRNA hsa-mir-3614-5p scramble, agomir, or antagomir elicited dissociated effects (top row right)." (PMID 32899117, 2020). "Third, we used a Bmal1:dluciferase (Bmal1:dluc) U2OS (human osteosarcoma) cell line that has been used in cell-based circadian rhythm screens." (PMID 31455847, 2019). "In the U2OS osteosarcoma line, BMAL1 over-expression induces apoptosis, while in CA46 lymphoma cells it increases apoptosis and reduces proliferation, leading to smaller tumours when the cells are injected into mice." (PMID 30348208, 2018). "Using a human osteosarcoma U2OS cell line stably expressing the clock reporter Bmal1‐dLuc, we screened over 1,000 molecules from an FDA‐approved drug library and the IDC to identify new circadian clock modulators." (PMID 29666146, 2018). "In contrast, Bmal1 suppression by siRNA attenuates the anti-proliferative effect of MLN4924 in U2OS osteosarcoma cells, indicating that the MLN4924-mediated cell growth inhibition is mediated by Bmal1." (PMID 27602774, 2016). "Downregulation of RORα or Bmal1 in U2OS osteosarcoma cells attenuates the MLN4924-induced cell growth suppression as well as G2/M cell cycle arrest." (PMID 27602774, 2016). "Bmal1 was significantly up-regulated in osteosarcoma cells MG63, Saos-2, and U2OS after MLN4924 treatment." (PMID 27602774, 2016). "In U2OS osteosarcoma cells, Bmal1 protein levels were induced by MLN4924 in a concentration-dependent manner." (PMID 27602774, 2016). "In this system, Bmal1-dLuc reporter cells derived from human U2OS osteosarcoma cells show robust luminescence rhythms on 384-well plates by expressing a rapidly degradable luciferase under the control of a mouse Bmal1 gene promoter." (PMID 21179498, 2010). "A recent study used 137 crude drug extracts to identify circadian clock modulators using a human osteosarcoma U2OS cell line stably expressing the clock reporter BMAL1-dLuc, thus pointing to a putative involvement of plant extracts upon modulation of the circadian clock." (PMID 36012399, 2022). "In addition, BMAL1 is able to bind to the promoter region of Bnip3 in osteosarcoma according to ChIP-seq analysis." (PMID 32277346, 2020). "Human osteosarcoma (U-2 OS) reporter cells—an established and robust cellular clock model—expressing luciferase from a Bmal1 promoter fragment were transduced with up to three shRNA constructs per target gene, and circadian luciferase activity rhythms were monitored over a period of one week." (PMID 29377895, 2018).